IP6K1 (inositol hexakisphosphate kinase 1)
Description:
Converts inositol hexakisphosphate (InsP6) to diphosphoinositol pentakisphosphate (InsP7/PP-InsP5). Converts 1,3,4,5,6-pentakisphosphate (InsP5) to PP-InsP4.
Synonyms: IHPK1; KIAA0263; PiUS
Tractability: Small molecule: a high-quality ligand is known. PROTAC: ubiquitination databases record sites on it; its protein half-life has been measured; a small molecule that binds it is known.
Target class: Enzyme; Transferase
Gene: Protein-coding gene on chromosome 3 (49,724,294 to 49,786,546, reverse strand). Ensembl gene ENSG00000176095.
Subcellular location: Cytoplasm; Nucleus
Subcellular location (Human Protein Atlas): Nucleoli fibrillar center; Cytosol; Nucleoplasm
Pathways (Reactome):
Metabolism: Synthesis of IPs in the nucleus; Synthesis of pyrophosphates in the cytosol
Gene Ontology:
Molecular function: inositol hexakisphosphate kinase activity; protein binding; diphosphoinositol pentakisphosphate kinase activity; diphosphoinositol tetrakisphosphate kinase activity; inositol 5-diphosphate pentakisphosphate 5-kinase activity; inositol-1,3,4,5,6-pentakisphosphate kinase activity; inositol hexakisphosphate 5-kinase activity; kinase activity
Biological process: phosphatidylinositol phosphate biosynthetic process; inositol phosphate metabolic process; negative regulation of cold-induced thermogenesis; inositol phosphate biosynthetic process; organophosphate biosynthetic process
Cellular component: cytosol; fibrillar center; nucleoplasm; cytoplasm; nucleus
Genetic constraint (gnomAD): Loss-of-function variants: 13 observed, 40.02 expected, observed/expected ratio (o/e) 0.32, 90% interval 0.21 to 0.52. The upper end of that interval is the gene's LOEUF score, 0.52, which puts it in group 2 of 6, group 1 being the genes least tolerant of losing a copy. Missense variants: 397 observed, 627.96 expected, observed/expected ratio (o/e) 0.63, 90% interval 0.58 to 0.69. Synonymous variants: 212 observed, 243.79 expected, observed/expected ratio (o/e) 0.87, 90% interval 0.78 to 0.97.
Homologues: Orthologues: chimpanzee IP6K1 (99% identical), macaque IP6K1 (99% identical), pig IP6K1 (97% identical), dog IP6K1 (96% identical), rabbit IP6K1 (96% identical), mouse Ip6k1 (95% identical), rat Ip6k1 (95% identical), guinea pig IP6K1 (93% identical), tropical clawed frog ip6k1 (74% identical), zebrafish ip6k1 (72% identical), Drosophila melanogaster Ip6k (34% identical), Caenorhabditis elegans F30A10.3 (29% identical), and 2 more. Paralogues in human: IP6K3 (47% identical), IP6K2 (46% identical), IPMK (19% identical), ITPKB (18% identical), ITPKC (17% identical), ITPKA (16% identical).
Diseases named in the same sentence as IP6K1 in open-access papers:
IP6K1 is named in the same sentence as 44 diseases in open-access papers, as found by Europe PMC text mining. Sharing a sentence is not in itself a finding about the gene and the disease. The quoted sentences say what the papers report.
Obesity (21 papers, 2012 to 2025). Accumulation of substantial excess body fat. "IP6K1 was also shown to play a vital role in regulating bone marrow mesenchymal stem cells in mice, in which IP6K1 is identified as a therapeutic target to avoid skeletal involution (continuous bone loss) in response to high-fat diet and obesity." (PMID 38403246, 2024). "To determine if IP6K1 inhibition in obese mice affords protection against obesity-induced metabolic derangements and bone loss, we maintained 2-month-old mice on a normal chow control diet or HFD under thermal neutral conditions for 100 d." (PMID 36138736, 2022). "It has been investigated as a therapeutic target for obesity and type 2 diabetes and variants within the IP6K1 gene region have been previously identified, using tag SNP analysis, as being associated with AD." (PMID 32429992, 2020). "A recent study has demonstrated that inhibiting IP6K1 in mice prevents obesity-induced bone loss." (PMID 38403246, 2024). "To assess impacts of IP6K1 inhibition on obesity-induced bone loss, we subjected 2-month-old mice to HFD feeding for 100 d under thermo-neutral conditions to prevent adaptive thermogenesis and after 40 d administered daily injections of vehicle or TNP (10 mg/kg BW)." (PMID 36138736, 2022). "Inhibition of IP6K1 helps maintain insulin sensitivity and prevents obesity whilst preserving bone integrity." (PMID 40108027, 2025). "Insights from recent studies indicate that IP6K1 plays a pivotal role in regulating metabolic processes such as insulin secretion and obesity." (PMID 40573111, 2025). "In this context, Inositol hexakisphosphate kinase 1 (IP6K1) has been considered a potential target in treating obesity, metabolic diseases, and more recently bone disorders." (PMID 40573111, 2025). "Conversely, the deletion of IP6K1 offered protection to insulin resistance and reduced high-fat-diet obesity and fatty liver in mice." (PMID 38397389, 2024). "IP6K1 protein levels are increased in obesity, and patients with nonalcoholic fatty liver disease, which is associated with reduced plasma levels of apoA-I and HDL." (PMID 39643078, 2024). "Based on these findings, the inhibition of IP6K1 using selective inhibitors provides a potentially efficient approach to manage obesity and type 2 diabetes." (PMID 38403246, 2024). "Our investigation not only contributes to the design of novel IP6K1 inhibitors but also holds promise in the quest to combat obesity." (PMID 38399478, 2024). "Ip6k1 deletion has been shown to have beneficial effects on diet- and age-induced obesity, insulin resistance, NAFLD/NASH, osteoporosis, pneumonia, and thromboembolism." (PMID 37238737, 2023). "In high-fat diet-fed mice, IP6K1 promotes obesity and insulin resistance by reducing insulin signaling and thermogenic energy metabolism in adipose tissue and liver." (PMID 35216174, 2022). "Inositol hexakisphosphate kinase 1 (IP6K1) functions as a prominent regulator of energy expenditure based on data showing its inhibition protects mice from diet-induced obesity." (PMID 36138736, 2022). "Epidemiologic data have linked IP6K1, the major IP6K isoform, to obesity in humans, and genetics-based studies have identified the kinase as a critical driver of metabolic disease, insulin resistance, and fatty liver in rodent models of DIO." (PMID 36138736, 2022). "Using various knockout mouse models, we previously discovered the inositol pyrophosphate (5-IP7) biosynthetic enzyme inositol hexakisphosphate kinase 1 (IP6K1) as a novel target in high-fat diet-induced obesity." (PMID 35216174, 2022). "An epigenome-wide association study identified higher CpG methylation upstream of Ip6k1 in the saliva of overweight adolescent Finnish girls compared to lean girls, suggesting diminished expression of the gene in obesity." (PMID 32204420, 2020). "In summary, whole body Ip6k1-deletion protects mice from obesity, T2D and NAFL due to increased energy expenditure." (PMID 32204420, 2020).
Obesity (continued). "In line with this, high-fat-diet-fed IP6K1 KO mice are protected from obesity, hyperinsulinemia, hyperglycemia, hepatic steatosis, and insulin resistance." (PMID 32397291, 2020). "Genetic deletion of Ip6k1 protects mice from high fat diet induced obesity, insulin resistance and fatty liver." (PMID 32204420, 2020). "IP6K1−/− mice can avoid weight gain and insulin resistance caused by high-fat feeding, owing to the activation of the AKT pathway, therefore inhibition of IP6K1 can be used as a strategy for the treatment of obesity and diabetes." (PMID 33362729, 2020). "In obesity, IP6K1/5-IP7 mediated peripheral insulin resistance causes hyperglycemia, which further stimulates IP6K1/5-IP7 induced insulin secretion from β cells, resulting in hyperinsulinemia induced lipogenesis." (PMID 32204420, 2020). "On the contrary, IP6K1 knockout mice manifest insulin sensitivity and are resistant to obesity elicited by high-fat diet or aging." (PMID 30595691, 2018). "Overall, these studies highlight that inhibition of IP6K1 in peripheral tissues may constitute a therapeutic approach to treating both obesity and diabetes." (PMID 41032702, 2025). "Interestingly, IP6K1 knockout in mice results in improved insulin sensitivity and energy expenditure, providing protection against diet-induced obesity, hyperinsulinemia, and insulin resistance." (PMID 38399478, 2024). "In addition to insulin secretion, IP6K1 was also shown to play a role in osteoporosis, aging, insulin resistance and obesity." (PMID 38403246, 2024). "The pharmacological roles of IP6K1 have undergone extensive exploration in recent years, with emerging evidence suggesting that inhibitors of this kinase and its isoforms hold promise for the treatment of obesity and related metabolic disorders." (PMID 38399478, 2024). "Consequently, high-fat diet-fed, whole-body- or adipocyte-specific Ip6k1-KO mice are protected from obesity, hyperinsulinemia, insulin resistance, and hepatic steatosis." (PMID 35216174, 2022). "Accordingly, Ip6k1 deletion diminishes insulin secretion whereas transgenic mice that express a hyperactive IP6K1 display augmented insulin release, congenital hyperinsulinemia, and obesity." (PMID 35216174, 2022). "Increased energy expenditure protects Ip6k1-KO mice from obesity, insulin resistance and NAFL." (PMID 32204420, 2020). "Genetic deletion of Ip6k1 or Ip6k3 or pharmacologic disruption of IP6Ks protects mice from metabolic diseases including obesity, type-2 diabetes (T2D), non-alcoholic fatty liver (NAFL), osteoporosis, myocardial infarction, ischemia reperfusion injury and aging." (PMID 32204420, 2020). "Thus, Ip6k1-KO mice are protected from high fat diet induced obesity partly due to increased adipocyte browning mediated thermogenesis." (PMID 32204420, 2020). "In other words, type 2 diabetes, obesity, and non-alcoholic fatty liver might be ameliorated by IP6K1 deletion." (PMID 33139672, 2020). "Taken together, the ablation of IP6K1 might have the advantages in decreasing obesity, improving metabolic parameters, and increasing thermogenic energy metabolism." (PMID 33139672, 2020). "Ip6k1-KO mice are protected from obesity, insulin resistance and NAFL." (PMID 32204420, 2020). "With the evidence presented above, it is hypothesized that IP6K1 has a role in this diminished response to anabolic stimuli, similar to the onset of insulin resistance, and obesity." (PMID 31552262, 2019). "It would be of great interest to see if IP7 signaling downstream of IP6K1 could uncouple the link between obesity, regulation of the Akt cascade, and tumorigenesis." (PMID 23050962, 2012). "Thus, IP6K1 is considered a target in obesity and type 2 diabetes." (PMID 38403246, 2024).
Obesity (continued). "The inactivation of inositol hexakisphosphate kinase 1 (IP6K1) protects mice from high-fat-diet (HFD)-induced obesity (DIO) and insulin resistance by enhancing thermogenic energy expenditure, but the role of this kinase and the consequences of its inhibition on bone metabolism are unknown." (PMID 36138736, 2022). "In addition to IP6K1, IP6K3 was also associated with obesity and insulin resistance regulation." (PMID 33139672, 2020). "Furthermore, IP6K1 deletion in mice ameliorates aging-induced obesity and insulin resistance." (PMID 32397291, 2020). "Inositol hexakisphosphate kinase-1 (IP6K1), an inositol pyrophosphate biosynthetic enzyme, is a target in diet-induced obesity (DIO) and obesity-related metabolic diseases." (PMID 37238737, 2023). "Inhibition of IP6K1 using N2-(m-Trifluorobenzyl), N6-(p-nitrobenzyl) purine (TNP) prevents diet induced obesity in mice through increased Akt activity." (PMID 31552262, 2019). "Mice with IP6K1 deletion or pharmacological IP6K inhibition show improved insulin sensitivity and are resistant to diet-induced obesity, which has been attributed to AMPK activation and thermogenic energy expenditure in adipose tissue, and potentially to enhanced adipose tissue lipolysis." (PMID 41032702, 2025). "Obesity also has negative impacts on male fertility, but prolonged IP6K1 inhibition had no adverse impacts on male reproductive parameters." (PMID 36138736, 2022). "Together, these data indicate that the inhibition of IP6K1 using selective inhibitors, such as TNP, may provide an effective strategy to manage obesity and T2DM due to its bone sparing effects." (PMID 36138736, 2022). "TNP’s anti-obesity effects are impaired but not abolished at thermoneutral temperature conditions, which further indicates that IP6K1 regulates energy expenditure in organs other than adipose tissue." (PMID 32204420, 2020). "The published studies on IP6K1 used a high fat diet without added cholesterol or fructose that develops obesity and NAFL, but not a full spectrum of NAFLD/NASH that includes inflammation, ballooning, stellate cell activation and fibrosis." (PMID 32204420, 2020). "When IP6K1 is deleted in adipocytes, mice exhibit enhanced thermogenic energy expenditure, which is protective against high-fat-diet-induced obesity at ambient, but not thermoneutral, temperatures." (PMID 32397291, 2020).
Insulin resistance (15 papers, 2016 to 2024). Increased resistance towards insulin, that is, diminished effectiveness of insulin in reducing blood glucose levels. "Moreover, the overactivation of IP6K1 is strongly associated with both insulin resistance and weight gain." (PMID 37047265, 2023). "So, the improved insulin resistance through IP6K1 ablation might be associated with reduced Akt pathway." (PMID 33139672, 2020). "IP6K1 impairs insulin signaling by inhibiting the insulin effector protein kinase Akt, promoting high-fat diet-induced insulin resistance." (PMID 35216174, 2022). "IP6K1 is relevant in human metabolic diseases as its levels positively correlate with HOMA-IR (Homeostatic Model Assessment for Insulin Resistance) in prediabetic subjects and negatively corelate to insulin sensitivity." (PMID 35216174, 2022). "It discusses the mechanisms by which IP6Ks promote weight gain and insulin resistance and how IP6K1 activity regulates the cross-talk among metabolic tissues in healthy and metabolic disease conditions." (PMID 32204420, 2020). "Inositol hexakisphosphate kinase 1 (IP6K1) is a six carbon cylitol kinase which has recently been well documented in the attenuation of insulin resistance and type 2 diabetes." (PMID 31552262, 2019). "Consequently, inhibiting IP6K1 reduces body weight and insulin resistance in diet induced obese mice through the activation of AMPK and AKT." (PMID 38403246, 2024). "It was found that the IP7 produced by IP6K1 induces the secretion of insulin by β-cells and simultaneously inhibits the Akt protein kinase that signals insulin levels in metabolic tissues, leading to hyperinsulinemia and insulin resistance." (PMID 38397389, 2024). "As expected, IP6K1 inhibition efficiently counteracts insulin resistance and obesity." (PMID 37047265, 2023). "Moreover, Ip6k1 deletion blocked age-induced increase in body- and fat-weight and insulin resistance in mice." (PMID 35216174, 2022). "While work is ongoing to create a specific IP6K1 inhibitor for the treatment of insulin resistance this may prove difficult, as IP6K1 is also important in the regulation of phosphate homeostasis, which is discussed in more detail in a later section." (PMID 35743190, 2022). "Thus, IP6K1 promotes high fat diet induced hyperinsulinemia and insulin resistance in mice while its deletion has the opposite effects." (PMID 32204420, 2020). "Therefore, myo-Ins-dependent modulation of IP6K1 can contribute to mitigating insulin resistance." (PMID 37047265, 2023). "A small-scale study on individuals with insulin resistance found that IP6K1 levels (protein and mRNA) deceased under conditions of high intensity exercise that correlated with improved insulin signaling, supporting an antagonistic role for insulin signaling by IP6K1 in humans." (PMID 35743190, 2022). "The whole-body and adipocyte-specific deletion of Ip6k1 ameliorates DIO, insulin resistance, and hepatic steatosis." (PMID 37238737, 2023). "We previously discovered that the inositol pyrophosphate biosynthetic enzyme IP6K1 is a target in diet-induced obesity (DIO), insulin resistance, and NAFLD." (PMID 37238737, 2023).
type 2 diabetes (7 papers, 2009 to 2024). "This suggests a role for IP6K1 in diabetes, as also suggested by the finding that, in a human family suffering from type 2 diabetes mellitus, the IP6K1 gene is disrupted." (PMID 24152294, 2014).
diabetes (4 papers, 2014 to 2024). "Future research into the role of IP6K1 in diabetes-related atherosclerosis will deepen our understanding in the pathological mechanisms of atherosclerosis." (PMID 39643078, 2024). "IP6K1 has been recognized as a potential druggable target for diabetes." (PMID 39643078, 2024).
hepatocellular carcinoma (3 papers, 2020 to 2023). A malignant tumor that arises from hepatocytes. "IP6K1 has been implicated in human liver disease, as hepatic IP6K1 is upregulated in NASH, alcoholic cirrhosis, and hepatocellular carcinoma patients." (PMID 37238737, 2023). "Ip6k3 is upregulated in NAFLD patients, whereas Ip6k1 and Ip6k2 expression directly correlate with hepatocellular carcinoma (HCC)." (PMID 32204420, 2020). "The expression of Ip6k1 correlates inversely with insulin sensitivity, whereas both Ip6k1 and Ip6k2 expression directly correlate with hepatocellular carcinoma (HCC)." (PMID 32204420, 2020). "Moreover, IP6K1 is upregulated in the liver of NASH, cirrhosis, and hepatocellular carcinoma patients." (PMID 35216174, 2022).
colon carcinoma (2 papers, 2019 to 2022). "By using a syngeneic MC38 murine mouse colon carcinoma model, here we examined how host IP6K1 in the tumor microenvironment influences tumor growth." (PMID 35308129, 2022). "Most notably, we observed that tumor tissues of MC38 colon carcinoma in IP6K1 KO mice showed very little CD11c+ dendritic cell infiltrate." (PMID 35308129, 2022). "We used CRISPR and the human colon carcinoma line HCT116 to create a cell line truly devoid of PP-IPs by disrupting both IP6K1 and IP6K2." (PMID 31186349, 2019).
infertile (2 papers, 2018 to 2022). "The infertility of IP6K1 KO mice is evidently caused by deficits in both quantity and quality of sperm." (PMID 29728588, 2018).
invasive carcinoma (2 papers, 2016 to 2022). A carcinoma that is not confined to the epithelium, and has spread to the surrounding stroma. "However, invasive carcinoma, defined by the migration of dysplastic epithelial cells into subepithelial tissues, was less in case of Ip6k1−/− mice, suggesting that these mice are protected against 4NQO induced carcinogenesis." (PMID 27140681, 2016). "Our results upon feeding the same carcinogen to Ip6k1 knockout mice revealed that unlike IP6K2, the loss of IP6K1 protects them from invasive carcinoma, underlining the fact that IP6K1 and IP6K2 have distinct roles in carcinogenesis." (PMID 27140681, 2016). "Therefore, the development of an isoform-specific IP6K1 inhibitor may provide a novel route to prevent the progression of epithelial dysplasia to invasive carcinoma." (PMID 27140681, 2016). "Moreover, IP6K1 knockout (KO) in mice protects against 4-nitroquinoline-1-oxide (4-NQO)–induced carcinogenesis and diminishes the progression of invasive carcinoma, suggesting IP6K1’s pro-tumorigenic action in cancer cells." (PMID 35308129, 2022). "When fed an oral carcinogen, mice lacking IP6K1 show reduced progression from epithelial dysplasia to invasive carcinoma." (PMID 27140681, 2016). "Our study reveals that IP6K1 facilitates the migration and invasion of cancer cells, so that mice lacking IP6K1 show reduced progression from epithelial dysplasia to invasive carcinoma upon chronic exposure to an oral carcinogen." (PMID 27140681, 2016). "Mice lacking IP6K1 are protected from invasive carcinoma induced by an oral carcinogen, suggesting that IP6K1 inhibition may provide a novel path to suppress cancer progression." (PMID 27140681, 2016). "However, unlike IP6K2, IP6K1 is essential for 4NQO-induced invasive carcinoma." (PMID 27140681, 2016).